CCR2 (C-C motif chemokine receptor 2)
Diseases named in the same sentence as CCR2 in open-access papers (continued):
Sharing a sentence is not in itself a finding about the gene and the disease.
infection (continued). "Knockout of CCL2 or CCR2 significantly impaired BMM infection measured by EGFP expression." (PMID 37085605, 2023). "This subpopulation expresses chemokine receptor type 5 (CCR5) as the primary HIV-1 acceptor, as well as lower levels of CCR2 in contrast to classical monocytes, which induces this type of monocytes to move to the site of infection and invade tissues through CCR2/chemokine ligand 2 (CCL2)." (PMID 35479083, 2022). "Ccr2-DTR mice treated with DT were much more susceptible to VACV∆C7L infection compared with WT mice treated with DT, with more rapid weight loss and 100% mortality at day 7 or 8 post infection." (PMID 35351885, 2022). "Calculating the differentially expressed genes revealed that genes such as Nkg7, Lgals1, Pdcd1, and Ccr2 were significantly upregulated in expanded cells in at least one infection condition and demonstrated consistent trends in expression for all infection groups." (PMID 35185882, 2022). "In this study, we demonstrated the expression levels of CCR2 in bone marrow, peripheral blood and small intestine are significantly affected by E. hellem infection and are consistent with the expression change patterns of Ly-6C on monocytes after infection." (PMID 36015036, 2022). "We speculate that CCL2 and CCL7 produced by lung AECIIs upon VACV∆C7L infection are likely to be involved in the recruitment of CCR2+Ly6C+ monocytes into the infected areas in the lungs." (PMID 35351885, 2022). "Monocytes egress from the bone marrow to the blood circulation in response to infection and they also migrate to the infected or inflamed tissue in a CCR2-dependent manner where they further differentiate into other cell types, including inflammatory DCs and macrophages." (PMID 35351885, 2022). "The change in corneal pathology of the OPN KO mice aligned with a decrease in total leukocyte infiltration into the cornea and specifically, in neutrophils at day 3 post infection and in macrophage subpopulations including CCR2+CD115+CD206+ and CD115+CD183+CD206+ -expressing cells." (PMID 36685562, 2022). "However, at day three post infection, the CCR2-GFP+ monocytes were diffusely localized in the alveolar area." (PMID 35351885, 2022). "Although monocyte-derived CD11c+ DCs are essential for priming a protective CD8 T-cell response to this infection, mice lacking CCR2 show better survival, reduced weight loss, and increased clearance of Yersinia from the mesenteric lymph nodes." (PMID 33829283, 2021). "Thus, in order to further explore the role of CCR2 in MGC formation at later stages of infection, we analyzed M.tb infected Ccr2−/− mice from day 60 to day 300 p.i.." (PMID 33795674, 2021). "A key function of CCR2 is enabling the rapid movement of inflammatory monocytes out of the bone marrow into the peripheral blood and tissues in response to inflammation and infection." (PMID 33760886, 2021). "Surprisingly, mice that were deficient in MCP-1/CCL2, MCP-3/CCL7, and MCP-5/CCL12, individually or collectively, were not nearly as susceptible to ID LVS infection as CCR2 KO mice." (PMID 33760886, 2021). "In contrast to Baft3-/- mice that have non-healing but stable lesions, monocyte-deficient ccr2-/- mice have highly significant deficiencies in iNOS+ cells and succumb to progressive disease at the late stages of infection in otherwise resistant C57BL/6 mice." (PMID 34557194, 2021). "Instead, CCR2 KO mice given a sublethal low dose ID LVS infection produced abundant and indeed increased serum anti-Francisella IgG antibodies, suggesting good development of helper T cells, and readily survived the largest available lethal LVS challenge dose as well as wild type mice." (PMID 33760886, 2021). "This suggests that CD11b+CCR2+Ly6ChiLy6G− cells give rise to M2 macrophages in this infection." (PMID 34684235, 2021).
infection (continued). "In order to reveal a possible mechanism involved in the failure to recruit innate immune cells in the absence of STAT1 at 2 days post-infection, we analyzed the expression of CCR2, a chemokine receptor associated with the recruitment of inflammatory monocytes." (PMID 34684235, 2021). "We reveal a role for CCR2 in formation of interstitial lung lesions, in shaping pulmonary and blood myeloid compartments and local pathogen defense, in a model of self-healing intradermal Orientia mouse infection." (PMID 34290699, 2021). "Nonetheless, the substantial susceptibility of CCR2 KO mice to ID LVS infection seems unlikely to be completely explained by chemokine excess." (PMID 33760886, 2021). "Notably, genes encoding the Th1-attracting chemokine CXCL9 (Cxcl9) and the CCL2 receptor, CCR2 (Ccr2), were found to be downregulated in both mouse strains after infection, but this downregulation was greater in BALB/c macrophages." (PMID 33617537, 2021). "Therefore, although CCR2 KO mice are exquisitely susceptible to primary ID LVS infection, once vaccinated by primary LVS infection, normal and protective adaptive immune memory responses can be generated in the absence of CCR2." (PMID 33760886, 2021). "Macrophages may protect the ear from nearby infection-prone areas by quickly recruiting “inflammatory” CCR2+ monocytes which can also lead to injury." (PMID 34880828, 2021). "CCR2 is the major chemokine receptor that regulates appropriate trafficking of inflammatory monocytes, but the role of this chemokine receptor and its ligands during primary and secondary infection with intracellular infections remains incompletely understood." (PMID 33760886, 2021). "Upon infection, the neutrophil numbers increased at 8 and 9 days p.i. in both the WT and KO group, whereas at 12 days p.i., less neutrophils were present in the lungs of the CCR2 KO mice compared to the WT mice." (PMID 33664739, 2020). "The intravascular lung Mo displayed limited activation capacity, impaired phagocytic functions and failed to transfer efficient protection against a secondary infection into monocytopenic CCR2-deficient mice." (PMID 32425929, 2020). "Resident dermal Mφ were sorted from S. aureus infected and control Ccr2-/- mice, which were used in order to specifically analyze the memory program in resident dermal Mφ, which – - essentially mediate increased resistance to a secondary infection." (PMID 32639232, 2020). "Interestingly, the reappearance of pulmonary eosinophils, after their decrease during infection, was mitigated in CCR2 KO mice." (PMID 33664739, 2020). "Nonetheless, our study found that CCR2 surface levels were similar between septic shock and infection groups and, like CD64 receptors, both infection and septic shock status could predict CCR2 surface levels over time." (PMID 33424860, 2020). "CCR2 deficiency was associated with significantly lower numbers of inflammatory monocytes in the lungs during infection and resolution and abolished the increase in non-classical monocytes during resolution." (PMID 33664739, 2020). "The recruitment of these permissive monocytes and their function at the infection site can be inhibited by morpholinos against either ccr2 or its ligand, ccl2, but the role of the Ccl2–Ccr2 signaling axis in other inflammatory responses is unknown." (PMID 31932292, 2020). "To determine how TRPM2 channel modulates the innate inflammatory response induced against L. monocytogenes infection, we infected C57BL/6 (WT), Trpm2−/− or Ccr2−/− mice with a sublethal dose of L. monocytogenes (104 CFU) and evaluated the susceptibility of Trpm2−/− mice to infection." (PMID 32117251, 2020). "To examine whether virus-specific CD8+ T cell priming by moDCs leads to enhanced protection against rechallenge, we harvested CD45.1+ effector P14 cells from WT or Ccr2−/− mice on day 8 post LCMV-Arm infection." (PMID 31474983, 2019). "The chemokine CCL2 (= MCP-1) attracts CCR2+ monocytes to sites of infection." (PMID 30800124, 2019).
infection (continued). "In addition, the frequency of KLRG1−CD127+ cells, which represent memory precursor cells (MPECs), was significantly reduced in Ccr2−/− hosts, suggesting that CCR2+ cells contributed to the efficient generation of memory CD8+ T cells during infection." (PMID 31474983, 2019). "In response to infection CCR2-positive monocytes can be recruited in large numbers and in the lung in particular this can cause widespread damage as they appear to be less likely than in the skin for example to convert to M2 macrophages associated with wound healing and repair." (PMID 31700522, 2019). "During infections, macrophages are often recruited to the tissue in a CCR2-dependent manner." (PMID 31455692, 2019). "Anti-CCR2 was administered daily from day 31–34-post infection and PLEC were examined at day 35 pi." (PMID 29299998, 2018). "In addition, B4GALT5 up-regulated the expression of chemokines (MCP-1) and receptor (CCR2), which attract more cells to migrate to the site of infection." (PMID 29546034, 2018). "Similarly, earlier studies have reported that CD16+ subset upregulates CCR2 expression during disease severity which aims to improve their migration ability toward the infection." (PMID 30105020, 2018). "Interestingly, during filarial infection of the pleural cavity of BALB/c mice, the relative proportions CCR2-monocyte recruited macrophages increases relative to resident proliferating populations as chronicity of infection progresses." (PMID 29547639, 2018). "Moreover, CCR2+ monocytes have been previously shown to be important innate cells that contribute to defense against infection with C. neoformans (15, 16, 51, –, 55)." (PMID 29317510, 2018). "Specifically, monocyte-derived dendritic cell-like, Ly6C+CCR2+ monocytes with high CD11c expression were harboring parasites with the highest proliferation rates at the site of infection, and were highly overrepresented among infected cells in the acute infection." (PMID 30346994, 2018). "CCR2 deficiency did not affect IFNγ production by NKT cells at 24 hours post-infection, but was associated with a significantly reduced percentage and total number of IFNγ+ γδ T cells." (PMID 28384349, 2017). "Transient fusion of infected macrophages with CCR2+ monocytes enabled bacterial transfer and subsequent dissemination, and interrupting this transfer so as to prolong mycobacterial sojourn in resident macrophages promoted clearing of infection." (PMID 28844797, 2017). "We next assessed whether depletion of CCR2+ cells affected virus-induced disease severity or viral burdens at later times post-infection." (PMID 29244871, 2017). "In addition to TNF, Ccr2-/- mice also had a significant defect in IL-12p70 and IL-12p40 production at both 24 and 48 hours post-infection, in agreement with recent findings." (PMID 28384349, 2017). "To determine whether classical monocytes contribute to the FXYD5-induced inflammatory response, we infected mice with Ad-FXYD5 or Ad-Null, and 48 h after the infection depleted monocytes by the injection of an anti-CCR2 antibody." (PMID 28620381, 2017). "Finally, reconstitution of Irf3-/-;Irf7-/- mice with CCR2-DTR bone marrow rescued mice from severe infection, and this effect was reversed by depletion of CCR2+ cells, indicating that CCR2+ hematopoietic cells are capable of inducing an antiviral response." (PMID 29244871, 2017). "Though Ccr2-/- mice showed no reduction in total DC numbers in the lung at 24 hours post-infection, DCs were significantly reduced in Ccr2-/- mice at 48 hours post-infection, consistent with previous findings that Ly6Chi monocytes differentiate into DCs at sites of inflammation." (PMID 28384349, 2017). "Indeed, following L. pneumophila infection, Ccr2-/- mice had a significant defect in recruiting Ly6Chi monocytes to the lung at 24 and 48 hours post-infection compared to B6 mice." (PMID 28384349, 2017).
infection (continued). "We next employed CCR2-diptheria toxin receptor (DTR) mice in which CCR2 expressing cells also express the DT receptor to formally demonstrate the role of CCR2+ cells at secondary sites of infection." (PMID 28666021, 2017). "Furthermore, reconstitution of Irf3-/-;Irf7-/- mice with CCR2-DTR bone marrow rescued mice from severe infection, and this effect was reversed by depletion of CCR2+ cells, indicating that CCR2+ hematopoietic cells are capable of inducing an antiviral response." (PMID 29244871, 2017). "As reported, the colonization of Streptococcus pneumoniae is gradually cleared through phagocytosis by monocytes/macrophages, which are recruited to sites of infection through their expression of the chemokine receptor CCR2 and correlated with its ligand MCP-1/CCL220." (PMID 28165033, 2017). "Depletion of CCR2+ moDCs at later stages of infection, leads to a skewing from a Th1 to a Th17 response in the lung, which indicates that recruitment of monocytes has an influential role in shaping the adaptive immune response and are necessary to promote and sustain Th1 responses." (PMID 26973640, 2016). "Mosquito bites also significantly enhanced infection with BUNV in a CCR2-dependent manner." (PMID 27332734, 2016). "We cannot exclude that CCR2-positive cells detected in brains of WT and WT→CCR2-/- animals could be blood leucocytes, which are known to infiltrate the CNS following infection with HSV-1 in our mouse model of HSE." (PMID 27930721, 2016). "CCR2 deficiency in resident cells of the CNS (WT→CCR2-/-) also increased susceptibility to the infection but the mortality rate was not statistically different compared to WT (42.8%; P = 0.16)." (PMID 27930721, 2016). "Indeed, levels of inflammatory monocytes were decreased prior to and following infection in the blood of CCR2-/- and CCR2-/-→WT mice." (PMID 27930721, 2016). "To distinguish among these possibilities, we performed 1:1 co-infection experiments with ΔdusB-fis in mice treated with an antibody, MC-21, which blocks the chemokine receptor CCR2 and prevents recruitment of Ly6Cpos inflammatory monocytes to tissue sites during microbial infection." (PMID 27689357, 2016). "By contrast, depletion with a combination of the MC-21 and 1A8 antibodies restored growth of ΔdusB-fis in livers and spleens, demonstrating that ΔdusB-fis is specifically sensitive to neutrophils and CCR2-recruited inflammatory monocytes during tissue infection." (PMID 27689357, 2016). "We found that IL-1α protein levels were significantly decreased when CCR2+ monocytes were absent consistent with the idea that lung-resident CCR2+ inflammatory monocytes are important for producing and/or inducing expression of this cytokine in the lung at early times after infection." (PMID 25629406, 2015). "Thus, either depletion approaches, anti-Gr1 or anti-CCR2 mAb, if performed early in infection, inhibited the development of ECM, which is paralleled by decreased infiltration of peripheral immune cells into the brains of PbTg infected mice." (PMID 25884830, 2015). "Because of the clear recruitment of Ly6C+ monocytes to the intestine following challenge, and the requirement for IL-4R-dependent alternatively activated macrophages (AAMs) in resistance to secondary infection with H. polygyrus, we vaccinated and challenged CCR2-/- mice." (PMID 25816012, 2015). "In this study, we provide evidence that CCR2+ monocytes are recruited to the intestinal lamina propria (LP) upon pathogen infection and rapidly give rise to a subset of intestinal MPs in situ that activate RORγt+ ILC3s through caspase-11 inflammasome-dependent IL-1β production." (PMID 26269452, 2015). "Furthermore, although both C57BL/6 mice and Ccr2-/- mice lost weight post infection, it was only until 6 dpi that a significant difference was observed." (PMID 26468944, 2015).
infection (continued). "Making use of the recent development of specific monoclonal antibodies (mAb), we depleted in vivo Ly6Chi inflammatory monocytes (by anti-CCR2), Ly6G+ neutrophils (by anti-Ly6G) or both cell types (by anti-Gr1) during infection with Ovalbumin-transgenic PbA parasites (PbTg)." (PMID 25884830, 2015). "Because aggressive recruitment of Gr1 + CD11b + cells was observed after day 3 post-infection, we wondered whether intranasal treatment with an anti-IFNAR1 blocking antibody at day 3 post-infection could interrupt the influx of CCR2+ inflammatory monocytes." (PMID 25407417, 2014). "Hence, in mice deficient for CCR2, a receptor for CCL2 and CCL8, the number and size of granulomas, as well as monocyte recruitment at site of infection, are decreased." (PMID 25566510, 2014). "Taken together, our results supported the concept that continuous recruitment of CCR2+ inflammatory monocytes by the IFNAR1-triggered chemokine feedback loop is attributable to the extended duration of IFNβ expression in the late phase of infection." (PMID 25407417, 2014). "Furthermore, similar numbers of neutrophils were present in the lung of CCR2 depleter and control mice at various times after infection." (PMID 24586155, 2014). "As NK cells and monocytes share their ability to proliferate in the BM during infection, we here aimed to identify whether CCR2 plays a key role in migration of NK cells also during influenza virus infection." (PMID 23272202, 2012). "However, adoptive transfer of CCR2-expressing monocytes into T. gondii infected CCR2−/− mice protected them from this otherwise lethal infection." (PMID 23094119, 2012). "Likewise, CCR2 KO animals did exhibit a significant decrease in the number of recruited Ly6c+/CD11b+/CD11c+ monocytes at day 9 PI in high dose infection." (PMID 23284825, 2012). "It is possible that the iNOS+ DC subset identified in vivo represents the inflammatory TipDC (TNFα+iNOS+CCR2+) which are recruited into the splenic T zone early during infection with Listeria monocytogenes or other pathogens as they were also CD11cint in our analysis (unpublished observation)." (PMID 22110693, 2011). "However, these are difficult experiments to perform because control animals are mostly dead at later stages of infection and there would be few control animals with which to compare the CCR2–/– mice." (PMID 21206747, 2010). "Since in CCR2 KO mice CD11b+Ly6C+ monocytic cells accumulated in the bone marrow, it was unclear whether CCR2 also played a role in blood to liver extravasation during infection." (PMID 20714353, 2010). "Chemokine receptor 2 (CCR2), expressed on immature dendritic cells (DCs), macrophages, monocytes, neutrophils, and activated T cells, guides monocyte migration from the bone marrow to infection sites, playing a crucial role in immune defense and the pathogenesis of inflammatory disorders." (PMID 39903705, 2025). "Similarly, the lack of monocytes in CCR2-deficient mice did not significantly impact CD4+ T cell polarization post-infection." (PMID 40169810, 2025). "Interestingly, CCR2-RFP cells were virtually undetectable in the brains of mice injected with 104 UV-treated or heat-killed parasites compared to i.c. infection with 200 live, replicating parasites." (PMID 40492741, 2025). "Although CCR2 is not a commonly used entry co-receptor for HIV in vivo, rare strains have been reported to utilize CCR2, and its primary role in HIV pathogenesis is linked to monocyte recruitment and inflammation, which may facilitate infection by attracting new target cells to infected tissues." (PMID 40909274, 2025). "However, it should be noted that the recruitment of neutrophils is also CCR2-dependent, and these cells were recruited already 24 h post infection, ruling out a gross defect on egress from the bone marrow as explanation to the delayed recruitment of inflammatory monocytes." (PMID 38578798, 2024).